PSEN1 (presenilin 1)
Diseases named in the same sentence as PSEN1 in open-access papers (continued):
Sharing a sentence is not in itself a finding about the gene and the disease.
progressive supranuclear palsy (1 paper, 2025). A rare late-onset neurodegenerative disease characterized by supranuclear gaze palsy, postural instability, progressive rigidity, and mild dementia. "Searching for other cases resulted in the identification of PSEN1 p.A79V in one possible AD patient, PSEN1 p.R269H and MAPT p.A60G in two independent MCI patients, and GBA1 p.W223R and APP p.A209T in two independent progressive supranuclear palsy (PSP) patients." (PMID 40813364, 2025).
renal carcinoma (1 paper, 2014). A carcinoma arising from the epithelium of the renal parenchyma or the renal pelvis. "Together, these findings indicate that blockage of MUC1-C nuclear localization either through inhibition of ADAM10 and PSEN1 expression or direct MUC1-C inihibitor are enough to significantly decrease renal cancer cell invasiveness." (PMID 24504508, 2014).
rosacea (1 paper, 2022). A chronic erythematous skin disorder that affects the face.
Seizure (1 paper, 2021). A seizure is an intermittent abnormality of nervous system physiology characterized by a transient occurrence of signs and/or symptoms due to abnormal excessive or synchronous neuronal activity in the brain. "Seizures have been reported in many PSEN1 mutations carriers." (PMID 33741601, 2021).
Splenomegaly (1 paper, 2021). Abnormal increased size of the spleen. "Interestingly the 5xFAD mouse model of AD, which has both APP and presenilin-1 gene modifications does not display splenomegaly." (PMID 34199639, 2021).
trisomy 21 (1 paper, 2020). A chromosomal disorder consisting of the presence of an extra chromosome 21. "Genetic mutations in the genes coding for presenilin 1 (PS1), presenilin 2 (PS2), amyloid beta precursor protein (APP), and Trisomy 21 may also be involved in the pathogenesis of AD." (PMID 33265993, 2020).
ventricular septal defect (1 paper, 2023). The presence of a defect (opening) in the septum that separates the two ventricles of the heart. "PSEN1 knockout mice presented several heart dysfunctions, such as ventricular septal defect (VSD) or double outlet right ventricle (DORV)." (PMID 37176125, 2023).
viral myocarditis (1 paper, 2019). Myocarditis that is caused by an infection with a viral agent. "In the present study, we sought to understand the role of NUP98 in the pathogenesis of viral myocarditis and its impact on the hypothetically cardioprotective NRG1-ERBB4/PSEN1 signaling axis." (PMID 31396490, 2019).
neurodegenerative disease (43 papers, 2012 to 2025). A disorder of the central nervous system characterized by gradual and progressive loss of neural tissue and neurologic function. "No additional pathogenic mutations were identified in other dominant causative genes of AD, FTD, or of other neurodegenerative diseases, such as PSEN1, PSEN2, PGRN, or MAPT on this patient." (PMID 30917570, 2019). "While Necab3, Apbb2, App, Psen1, Prkcg and Saa1 are associated with Aβ accumulation, Park2 and Snca are associated with protein aggregation in AD and PD, as well as other neurodegenerative diseases." (PMID 24278249, 2013). "As for the other neurodegenerative diseases, familial forms (FAD) account for only a minority of cases and the most common mutations are found in presenilin 1 (PSEN1), presenilin 2 (PSEN2), and the amyloid precursor protein (APP)." (PMID 39273694, 2024). "Of interest, Tyr phosphorylation levels were increased in AD and PSEN1 A246E patients when compared to patients affected by other neurodegenerative diseases." (PMID 33466666, 2021). "About half of the neurodegenerative disease-associated genes, namely APP, PSEN1, and PSEN2 for AD; C9orf72 and MAPT for FTD and SNCA; and PRKN and PARK7 for PD, have larger number of DPI robust TSSs than annotated CAT CAGE clusters." (PMID 30610612, 2019). "In addition, both amyloid-dependent and amyloid-independent pathways have been implicated in mediating its phenotypic effects, highlighting the complex and multifactorial role of PSEN1 in neurodegenerative disease." (PMID 40943910, 2025). "The influence of PSEN1 mutation on the pathogenicity of neurodegenerative diseases has not yet been well understood." (PMID 40943910, 2025). "Knockout of Nrmt1 in mice led to the inactivation of RB1 and eventually induced neurodegenerative diseases, while the AD-related gene presenilin 1 (PS1) could protect the anaphase neuronal death by inhibiting the phosphorylation of RB1." (PMID 38637503, 2024). "In a subsequent study, and following a similar strategy, Krasemann and colleagues isolated microglia and analyzed transcriptomes of different neurodegenerative diseases including AD (Amyloid precursor protein-Presenilin-1(APP-PS1) mice), ALS, and multiple sclerosis." (PMID 32709045, 2020). "To investigate the brain penetration of [18F]Favipiravir between normal and neurodegenerative disease conditions, we performed PET imaging studies with [18F]Favipiravir in transgenic AD mice (5 × FAD; strain name: B6SJL-Tg(APPSwFlLon, PSEN1*M146L*L286V)6799Vas/Mmjax) and wild-type (WT) mice." (PMID 37111280, 2023). "AD is a non-curable neurodegenerative disease with the majority of cases (85–90%) being sporadic and just 10–15% familial and caused by mutations in key genes such as Amyloid Precursor Protein (APP), Presenilin 1 (PSEN1), and Presenilin 2 (PSEN2), involved in the metabolic pathway of APP." (PMID 36231055, 2022).
cancer (19 papers, 2014 to 2025). A tumor composed of atypical neoplastic, often pleomorphic cells that invade other tissues. "Although most genes involved in tumorigenesis can be divided into tumor suppressor genes and oncogenes, PSEN1 cannot be clearly classified, because it exhibits two functions of promoting and suppressing cancer in different tumor-specific genetic damage." (PMID 37928268, 2023). "They believed that Presenilin-1 is associated with CAJ disassembly and can drive cancer progression by triggering TCF / LEF-1 activation." (PMID 36117156, 2022). "Despite still a preliminary stage of this study, we anticipate to deciphering a novel function of PSEN1, and supporting more researchers toward the elucidations of the mechanisms linking the γ-secretase to cancers, which has yet to be fully addressed." (PMID 36059511, 2022). "Overall, PSEN1 is still poorly studied in human tumors, and how it affects tumors in different cancers remains to be investigated." (PMID 36117156, 2022). "We profiled the expression of Presenilin 1 and Nicastrin in 19 cancers within the Cancer Genome Atlas (TCGA) database using TIMER2.0 online web server, demonstrating that both genes had significantly higher expression in the several cancer types examined." (PMID 34059639, 2021). "Levels of PSEN1 were negatively correlated with infiltrating CD8+ T (p<0.05) and CD4+ T helper (Th) 1 cells (p<0.001), while positively correlated with regulatory T cells (Tregs) (p<0.001) and cancer associated fibroblasts (CAFs) (p<0.001)." (PMID 36059511, 2022). "Furthermore, previous studies have identified FOXQ1, PSEN1 and COL1A1 as the major molecular targets of miR-133 underlying its inhibitory role in EMT and cancer progression 23-26." (PMID 34335946, 2021). "PSEN1 could be protective against cancer through epigenetic mechanisms." (PMID 37176125, 2023). "In cancer cells, TRAF6 also engages and activates proteolytic enzymes such as ADAM17/TACE and presenilin-1 (PSEN1 or PS1), which leads to the generation and release of the TGFβRI intracellular domain (TGFβRI-ICD)." (PMID 35625561, 2022). "Recently, miR-193a, miR-654-3p and other selective PSEN1 inhibitions have been reported to hamper gastric, SNSCC and Leukemias cancer hallmarks, respectively." (PMID 36059511, 2022). "Recent findings indicated that several proteases, including MMP-2, MMP-3, MMP-9, presenilin 1, and CD26, are promoters and mediators of EMT processes in different cancer types." (PMID 30134935, 2018). "During such a reversion, cancer cells re-express several previously repressed genes, including those involved in cell plasticity (Oct4, SOX-2, and Nanog), while genes (PSEN1, Notch-1) and proteins (SNAI1, αSMA, N-cadherin) supporting epithelial–mesenchymal transition (EMT) are downregulated." (PMID 37511359, 2023). "It should also be noted that PSEN1 plays an important role in various cancers, both dependent on and independent of γ-secretase activity." (PMID 37928268, 2023).
tumor (15 papers, 2017 to 2024). "In addition, the down-regulation of PSEN1 expression in cell line U937 led to slower proliferation and increased apoptosis of tumor cells, and the down-regulation of PSEN1 expression also reduced the tumor-causing ability in nude mice." (PMID 37928268, 2023). "Our study indicated that PRL and PSEN1 were associated with tumor fibrosis and that prolactin might be the key cytokine regulating tumor fibrosis." (PMID 34539753, 2021). "Collectively, the associations between rs165932 C allele with high tumour tissue levels of PSEN1 mRNA may have led to a better survival." (PMID 30055028, 2018). "In the light of our findings and the supporting documentations, we propose a model for PSEN1 to regulate tumor-immune interactions via influencing PD-L1 nuclear translocation." (PMID 36059511, 2022). "Of these eight genes, four (GNAI3, PCDH7, PSEN1, TNFSF9) were highly expressed in tumor tissues and were associated with poor prognosis, while CD69, SLC11A2, and TLR2 were poorly expressed in tumor tissue and were associated with good prognosis." (PMID 36117156, 2022). "PSEN1 plays an important role in tumor radio resistance, induce cell cycle arrest, and stimulate DNA damage response." (PMID 34925377, 2021). "An ASO blocking PSEN1 that was used in leukemic cell lines (K562 and U937) induces apoptosis, and reverts the tumor phenotype in the cell lines as well as in vivo in the SCID mouse model." (PMID 33958005, 2021). "Inhibition of γ-secretase’s activation has the important anti-tumor properties by blocking of the Notch pathway’s activation and repressing the expression of PSEN-1 is a promising approach for γ-secretase inhibition." (PMID 34169001, 2021). "The expression of miR-27-3p was lower in the TNBC specimens than in the paired non-tumor tissues, and the expression of miR-27-3p was negatively correlated with PSEN-1 in TNBC tissues." (PMID 34169001, 2021). "In an In vivo SCID mouse model, inhibition of PSEN1 led to suppression of tumor phenotype, retarded growth, and induction of apoptosis." (PMID 33958005, 2021). "Moreover, DNMT-1 expression was much higher in LSCC specimens than that in the paired non-tumor tissues and was positively correlated with PSEN-1 and N-cadherin expression, typical downstream factors of Notch pathway-related to EMT." (PMID 35401185, 2022). "Together, these data support potential actions of PSEN1 in tumor - immune interactions, which might confer an alternate escaping mode of PD-L1 against the host immunity." (PMID 36059511, 2022). "PSEN1 played an important role in tumor progression and drug resistance." (PMID 34568005, 2021). "Also, another pathway, the lncRNA H19/miR-193a-3p axis, has been found to induce therapeutic tolerance by targeting presenilin 1 (PSEN1), a key component of γ secretase, and then promote tumor aggravation." (PMID 32122355, 2020). "Finally, we quantified the protein level of PSEN1/PI3K-AKT signaling axis in the tumor tissue." (PMID 34568005, 2021). "PSEN1 is still poorly reported in lung tumors, and this study reveals for the first time that it is overexpressed in LUAD tumor tissues, and that its enhanced expression is correlated with a worse prognosis." (PMID 36117156, 2022). "To reveal the roles of Notch-related pathways in LSCC, we examined PSEN-1 expression in clinical specimens (i.e., the LSCC clinical specimens or the paired non-tumor tissues)." (PMID 35401185, 2022). "Differential analysis showed that GNAI3, PCDH7, PSEN1 and TNFSF9 were highly expressed in tumor tissues, while ADM, CD69, SLC11A2 and TLR2 were opposite." (PMID 36117156, 2022). "Given the potential interaction of PSEN1 with the cytoskeleton protein vimentin which is involved in mediating epithelial- to- mesenchymal transition (EMT) and metastasis, we thus interrogated the involvement of PSEN1 in tumor invasiveness." (PMID 36059511, 2022).
tumor (continued). "In addition, Cox proportional hazards regression analysis was performed for 5-year overall survival rates, using each gene expression level (i.e., PFN2, PSEN1, and SYT1), tumor stage, pathological grade, and age as covariates." (PMID 35327465, 2022). "However, a strongly positive gene correlation between PSEN1 and PD-L1 was verified by TIMER2 and GEPIA (p<0.001), and notably, this connection was tumor specific." (PMID 36059511, 2022). "Cleavage of TβR1 by ADAM17/TACE and Presenilin 1, a γ-secretase catalytic core component, has also been found in multiple cancer cell lines, which results in the translocation of the intracellular domain (ICD) of TβR1 into the nucleus and activation of genes involved in tumor invasion." (PMID 28068334, 2017).
infection (10 papers, 2018 to 2025). The state of being infected such as from the introduction of a foreign agent such as serum, vaccine, antigenic substance or organism. "To investigate the effect of AD-linked mutations on the pathogen infection, we extended our analysis to iPSCs derived from patients with familial AD, carrying mutations in PSEN1 (A246E) or PSEN2 (I144N)." (PMID 40661646, 2025). "However, previous research using AD animal models has indicated that 5xFAD mice (expressing human APP and PSEN1 with AD-linked mutations) exhibit a milder reaction to pathogen infections and survive longer, suggesting a potentially protective role of amyloids." (PMID 40661646, 2025). "In LRRK2, DJ-1, and PSEN1, for example, promoter-associated antisense lncRNAs are more expressed in blood libraries than in the brain, and within blood cells, their expression is strongly activated upon infection." (PMID 30610612, 2019). "SARS-CoV-2 infection resulted in a significant overexpression of Notch1, Notch2, CTNNB1, CDC42, and PSEN1 after 24 h of infection." (PMID 37211584, 2023). "MA10 infection resulted in six additional down-regulated (Cpe, B2m, Pltp, Sparc, Cldn5, Vtn) and four up-regulated DEGs (Slc2a1, Vim, Apod, Acta2), whereas Aβ pathology alone produced one down-regulated (Slc2a1) and three upregulated DEGs (Gfap, Psen1, Clu)." (PMID 41497643, 2025). "MA10 infection induced six down-regulated (Pllp, Malat1, Myrf, Mag, Ptgds, Ugt8a) and two upregulated DEGs (Sgk1, Mbp), while Aβ pathology resulted in one down-regulated (Hmgb1) and ten up-regulated DEGs (Apoe, B2m, Clu, Cstd, Gfap, Psen1, Pllp, Cst7, Cd9, Plp1)." (PMID 41497643, 2025). "PSEN1/2 mutations did not alter the acute infection response." (PMID 40661646, 2025). "The transcripts of APP, ADAM10, BACE1, and subunits of the γ-secretase complex (PSEN1, PSEN2 APH1A and NCSTN) were significantly upregulated (p < 0.05) in at least one of the 4 investigated timepoints post-infection." (PMID 30786875, 2019). "Based on our findings, we hypothesize that mutations in APP, MAPT, and PSEN1 genes yield a compounding effect with age, triggering biological changes which initiate an inflammatory response that mimics the effects of LPS stimulation, despite the absence of infection." (PMID 38909241, 2024). "MA10 infection induced seven additional down-regulated (Hsp90aa1, Tcf7l2, Gnas, Sparcl1, Ywhag, Cpe, Sparc) and four upregulated DEGs (Ppp1r1b, Penk, Arpp21, Pcp4), whereas Aβ pathology resulted in five down-regulated (Cplx1, Syp, Meg3, Snhg11, Penk) and one upregulated DEG (Psen1)." (PMID 41497643, 2025). "After infection, APP and BACE1 expression levels of fCBO were increased whereas γ-secretase complex proteins including PSEN1/2 levels were not." (PMID 36697403, 2023).
neurological disorders (10 papers, 2014 to 2025). "A focused examination of six AD-related genes – APOE, APP, BIN1, CLU, MAPT and PSEN1 – and SMARCA5, which has been linked to neurological disorders, revealed different expression patterns across cell types and AD." (PMID 41255979, 2025). "Of these, SH3BGRL3 has already been linked to SCZ and PSEN1, B9D2, and CXCR5 as well as DNAJB2 and were implicated in other neurological disorders." (PMID 36344995, 2022). "Moreover, PSEN1’s high pLI score, similar to genes involved in pediatric neurological disorders (e.g., PTEN), implies potential effects on critical biological pathways influencing both neurological development and reproductive fitness, highlighting its evolutionary significance." (PMID 40909785, 2025).
autosomal dominant disease (4 papers, 2017 to 2022). Autosomal dominant form of disease. "Extensive research has shown that early-onset AD (EOAD) is usually an autosomal dominant inherited disorder that represents about 1–2% of all cases and involves mutations in the gene’s amyloid precursor protein (APP), presenilin 1 (PSEN1), or PSEN2." (PMID 36142483, 2022). "One form of the disease is familial AD, a very rare pure autosomal dominant disease with early onset before 65 years, which is caused by mutations in amyloid precursor protein (APP), presenilin-1 (PS1) or presenilin-2 genes all connected to Aβ accumulation." (PMID 32646017, 2020).
brain disease (4 papers, 2016 to 2025). "Emerging studies have shed light on somatic mutations in brain diseases and brain aging, with one study particularly focusing on somatic PSEN1 mutations." (PMID 36142879, 2022). "Despite these advances, the lack of appropriate human cellular models, particularly for FAD PSEN1 E280A, has hampered further basic pathophysiological studies linking microglia to brain disease." (PMID 40806295, 2025). "Apolipoprotein E (ApoE), Presenilin-1 (PSEN1) and Presenilin-2 (PSEN2), amyloid precursor protein (APP) and the linked mutations are some of the strongest risk factors that were observed to be associated with the brain disorder, Alzheimer’s." (PMID 27756223, 2016).
metabolic disorders (4 papers, 2019 to 2025). "As mitochondrial dysfunction and subsequent metabolic disorders are observed in AD and changes in the PSEN1–NDUFAB1 gene pair affecting the mitochondrial function, we can speculate that a correlation exists between the PSEN1–NDUFAB1 gene pair and AD." (PMID 31736866, 2019). "Presenilin 1 (PSEN1), catalase (CAT), glutathione-S-transferase (GST) andparaoxonase 1 (PON1) play a vital role in prediction, diagnosis and therapyof metabolic disorders." (PMID 35976206, 2022).
genetic disorder (3 papers, 2013 to 2023). "Most patients who suffer from early-onset AD have familial AD (FAD), which is a hereditary disease associated with mutations in the genes involved in the production of Aβ peptides such as APP and presenilin-1 and 2 (PSEN1 and PSEN2)." (PMID 36367657, 2023).
cardiac disease (2 papers, 2021 to 2024). "Furthermore, PSEN1 expression was found to be downregulated in ischemia-induced HF, and PSEN1-deficient mice exhibited significant reductions in ejection fraction and fractional shortening percentage, suggesting that loss of PSEN1 may cause cardiac disease by interfering with calcium homeostasis." (PMID 39571156, 2024).
cardiovascular disease (2 papers, 2024 to 2025). "In summary, AD-causing genes including APP and PSEN1/2 are involved in the development of cardiovascular diseases, and their mechanisms need to be further investigated." (PMID 39571156, 2024). "A case-control study found that subjects with PSEN1 mutations leading to early onset of AD had a markedly elevated risk of cardiovascular disease." (PMID 39571156, 2024).